HMGB1 (high mobility group box 1)
Diseases named in the same sentence as HMGB1 in open-access papers (continued):
Sharing a sentence is not in itself a finding about the gene and the disease.
colorectal cancer (continued). "Recent clinical evidence showed that the overexpression of HMGB1 in colorectal cancer was related to malignant phenotypes and shorter survival times." (PMID 20846416, 2010). "Additionally, hsa-miR-582-5p functions as a binding partner for lncRNA DCST1-AS1, which is known to modulate the invasiveness of colorectal cancer (CRC) cells via the hsa-miR-582-5p/HMGB1 pathway." (PMID 40595862, 2025). "In colorectal cancer, NK cell‐derived HMGB1 sterically blocks pyruvate‐exporting PKM2 tetramers, forcing tumor cells to abandon OXPHOS and triggering metabolic apoptosis; resistant clones compensate by upregulating the glutamine‐ME1‐NADPH axis to replenish the TCA cycle, achieving metabolic escape." (PMID 41354099, 2025). "Previous research has confirmed that glycyrrhizin ameliorates colorectal cancer progression by regulating NHEJ pathway through inhibiting HMGB1‐induced DNA damage response and glycyrrhizin effectively reverses the cancer‐promoting effects of IGF2BP3 overexpression in bladder cancer." (PMID 39904827, 2025). "Furthermore, we observed a significant increase in HMGB1 released into the culture supernatant by colorectal cancer cells treated with recombinant adenoviruses compared to the ADVCtrl group." (PMID 40082916, 2025). "Our findings indicate that glycyrrhizin (GL), a key component found in licorice root, hinders the development of cancer by suppressing inflammation in a mouse model of colorectal cancer, since GL weakens the proinflammatory effects of HMGB1 by specifically binding GL to HMGB1." (PMID 40244228, 2025). "Furthermore, metformin synergizes with oxaliplatin by reducing HMGB1 expression, thereby enhancing cytotoxicity and overcoming resistance in colorectal cancer." (PMID 41465435, 2025). "Corresponding to this, HMGB1 also could promote tumor progression in colorectal cancer by activating EMT, Wnt, and ERK signal pathway." (PMID 38576043, 2024). "Likewise, HMGB1 released from colorectal cancer cells activates RAGE/ERK/Drp1, leading to cancer cell survival and resistance to chemotherapy." (PMID 38250151, 2024). "In colorectal cancer and gastric cancer, the HMGB1/RAGE axis also plays a role in tumor promotion." (PMID 38529373, 2024). "In colorectal cancer, the overexpression of HMGB1 and RAGE signaling may activate the transcription factor Yes-associated protein 1 (Yap1) through direct interaction with K-Ras, thereby promoting the proliferation and stemness of colorectal cancer cells." (PMID 38529373, 2024). "It has been reported that docetaxel [lung adenocarcinoma], oxaliplatin [colorectal cancer and lung carcinoma] and 5-FU [colon carcinoma cells] all induce tumour cell secretion of HMGB1." (PMID 35986757, 2023). "Here, we investigate the role of HMGB1—a multifunctional immune protein—in colorectal cancer." (PMID 36980751, 2023). "Oxaliplatin but not cisplatin was shown to trigger immunogenic cell death of colorectal cancer cells, activated dendritic cells by expressing danger signals such as heat shock proteins, calreticulin, HMGB1, and efficiently generated a pool of tumor antigen-specific T cells." (PMID 36899361, 2023). "We show an association between HMGB1 expression intensity and density of immune cell subsets in colorectal cancer; nuclear and cytoplasmic HMBG1 associated with increased CD4+ lymphocytes, and nuclear HMGB1 associated with increased FOXP3+ and ICOS+ lymphocytes and reduced CD8+ T-cells." (PMID 36980751, 2023). "Along similar lines, gas plasma-oxidized liquids have been shown to increase CRT and HMGB1 expression, as well as ATP release on and by colorectal cancer cells and others, followed by increased phagocytosis and expression of maturation markers on monocyte-derived dendritic cells." (PMID 35892641, 2022). "Our research shows that miR-495-3p inhibits the progression of colorectal cancer by downregulating the expression of HMGB1, which indicates that miR-495-3p may become a potential therapeutic target for colorectal cancer." (PMID 35354479, 2022).
colorectal cancer (continued). "In summary, our research shows that miR-495-3p inhibits the progression of colorectal cancer by downregulating the expression of HMGB1 in vivo and in vitro, which indicates that miR-495-3p may become a potential therapeutic target for colorectal cancer." (PMID 35354479, 2022). "Anticancer drugs that increase the release of the high-mobility group box 1 protein (HMGB1) trigger ERK1/2-mediated DRP1 phosphorylation in colorectal cancers, or increased ROS production and hypoxia in ovarian tumors, and are usually associated with fission-driven chemoresistance." (PMID 35326612, 2022). "HMGB1 is a prototypical damage-associated molecular pattern (DAMP) molecule that is released by induced autophagy and enhances treatment resistance in ovarian cancer, colorectal cancer, and lung cancer." (PMID 35326612, 2022). "The analysis of GO functional annotation/KEGG pathways indicates that HMGB1 may regulate tumor immunity-related pathways, such as the tumor immunotherapy response in colorectal cancer." (PMID 36230798, 2022). "Overexpression of HMGB1 plays an important role in the migration of cells, tumor progression, and metastasis in colorectal cancer; thus, it could be used as a predictor of disease outcome." (PMID 33807620, 2021). "Thus, it would be interesting to know which pathways of RAGE are activated by HMGB1 in colorectal cancer." (PMID 33117687, 2020). "In addition, studies have shown that upregulation of HMGB1 and RAGE has been linked with poor prognosis, metastasis, and tumor invasion in colorectal cancer." (PMID 33117687, 2020). "This study focused on the expression and changes of HMGB1 in the serum of colorectal cancer patients with liver metastasis before and after TACE, and we explored the possibility of predicting liver injury, adverse reaction, and PFS after TACE by monitoring the changes of HMGB1." (PMID 33473353, 2020). "HMGB1 is also found to act as a potent EMT driver in colorectal carcinoma and gastric cancer." (PMID 31558702, 2019). "Furthermore, the serum HMGB1 level was increased by 1.5-fold in patients with colorectal carcinoma compared to those in healthy controls." (PMID 30755156, 2019). "This hypothesis is supported by our findings in which HMGB1 was associated with autophagy and chemoresistance via RAGE/MEK/ERK/Drp1 in colorectal cancer." (PMID 30258050, 2018). "The silencing of HMGB1 also enhanced the sensitivity of colorectal cancer cells to OXP." (PMID 30258050, 2018). "In addition, the role of HMGB1 in drug resistance in tumours, including lung cancer, osteosarcoma, neuroblastoma, leukaemia, and colorectal cancer, has attracted broad attention." (PMID 29246127, 2017). "In addition, HMGB1 has been suggested to contribute to chemotherapy resistance in tumours, including lung cancer, osteosarcoma, neuroblastoma, leukaemia, and colorectal cancer." (PMID 29246127, 2017). "Recent studies showed that HMGB1 could promote chemotherapy resistance in colorectal cancer and lung adenocarcinoma through HMGB1 mediated autophagy." (PMID 25986235, 2015). "Both apoptotic and necrotic cells could stimulate proliferation of living tumor cells, and the increased expression of CC3 and HMGB1 in tumor cells could be new markers for poor prognosis in colorectal cancer patients." (PMID 25986235, 2015). "In addition, we also examined clinical colorectal cancer samples and found that HMGB1 is also a marker for poor prognosis." (PMID 25986235, 2015). "The increased expression of the key factors of apoptosis or necrosis such as CC3 and HMGB1 in tumor could be a new marker for poor prognosis in colorectal cancer." (PMID 25986235, 2015).
colorectal cancer (continued). "Clinicopathologic features of 219 colorectal cancer patients according to serum HMGB1 levels." (PMID 22496788, 2012). "To evaluate the diagnostic significance of secreted HMGB1 in vivo, we performed an ELISA assay using blood samples from 219 colorectal carcinoma patients and compared the values to those of 75 non-cancerous controls." (PMID 22496788, 2012). "To evaluate the diagnostic value of HMGB1, we performed an enzyme-linked immunosorbent assay to measure HMGB1 levels and compared them to carcinoembryonic antigen (CEA) levels in the serum samples of 219 colorectal carcinoma patients and 75 healthy control subjects." (PMID 22496788, 2012). "Furthermore, HMGB1 secreted from primary tumors decreased the number of macrophages to attenuate the anti-metastatic defense in patients with colorectal cancers, through inducing growth inhibition and apoptosis in macrophages." (PMID 20579387, 2010). "Furthermore, in an ischemia and reperfusion murine model, surgical stress caused NET formation that in turn promoted the development of liver metastases of colorectal cancer cells through the binding of NET-derived HMGB1 to TLR9 and activation of MAP kinases pathway." (PMID 41142788, 2025). "HMGB1 (High Mobility Group Box 1) is an oncogene that induces inflammation and facilitates tumorigenesis and metastasis and its downregulation by miR‐34a is sufficient to suppress proliferation, migration, and invasion of human cervical and colorectal cancer cells." (PMID 37042179, 2023). "HMGB1 may therefore represent a novel treatment target for colorectal cancer." (PMID 36980751, 2023). "CDK1, HMGB2, SSRP1, and H2AFV may serve as key nodes for HMGB1 in colorectal cancer." (PMID 36230798, 2022). "In addition, a stronger HMGB1 expression was evident in the esophageal tissues of the ESCC group than the adjacent tissue group concluding that our results in line with other reports observed with HMGB1 overexpression in cervical cancer, prostate cancer, and colorectal cancer." (PMID 35829833, 2022). "Therefore, this study may uncover a new mechanism that besides the caspase-3 from apoptotic cells, some other signal molecules, such as HMGB1 released from the necrotic cells, may also exert a role in the proliferation of living colorectal cancer cells." (PMID 25986235, 2015). "In murine (MC38) and human (HCT116) colorectal cancer cells, CF10 induced significantly higher levels of ICD markers-extracellular ATP, HMGB1 release, and surface calreticulin-than 5-FU and triggered robust Top1cc stabilization with γ-H2AX foci formation." (PMID 42019467, 2026). "BM-MSCs produced MT in colorectal cancer (CRC) cells damaged by 5-fluorouracil (5-FU), but were suppressed by the anti-high mobility group box-1 (HMGB1) antibody." (PMID 39940960, 2025). "This therapeutic effect is recently further demonstrated in colorectal cancer, where glycyrrhizin was shown to significantly downregulate the NHEJ pathway through direct inhibition of HMGB1, resulting in reduced cell viability and increased DNA damage." (PMID 41465435, 2025). "In colorectal cancer, APC gene deletion drives Wnt signaling pathway activation, which induces HMGB1 expression and secretion to maintain intestinal stem cells in a crypt progenitor‐like phenotype, thereby providing a cellular basis for tumorigenesis." (PMID 41354099, 2025). "Our own work has further expanded its therapeutic profile, demonstrating that HBHP disrupts the HMGB1-Hsp70 DAMP complex in lung and colorectal cancers." (PMID 41465435, 2025). "Glycyrrhizin, a direct HMGB1 inhibitor, suppresses NHEJ repair, induces DNA damage, restores caspase-3 activation, and triggers apoptosis in colorectal cancer models, illustrating the therapeutic value of targeting the HMGB1-driven survival network." (PMID 41465435, 2025). "All-thiol HMGB1 (at-HMGB1) binds to its receptor RAGE, promoting the secretion of the angiogenic factor VEGF, thereby facilitating angiogenesis in colorectal cancer patients." (PMID 38529373, 2024).
colorectal cancer (continued). "Most importantly, BTZ led to DNA damage–associated enhancement of immunogenicity, as indicated by the potentiated expression of HMGB1 and HSP90 in B-Myb–defective colorectal cancer, further driving M1 polarization of macrophages." (PMID 38565963, 2024). "The central role of the RAGE/HMGB1 axis in contributing to EMT in a PI3K/AKT-dependent manner widely documented in prostate cancer, and colorectal cancer." (PMID 35727208, 2022). "In colorectal cancer (CRC), LINC00460 was shown to serve as an oncogene of CRC that got involved in carcinogenesis by heightening the stabilization of HMGB1 at mRNA level." (PMID 35096063, 2022). "RAGE engagement by HMGB1, S100A8/A9, or S100P proteins can activate different oncogenic pathways, supporting the metastatic spread of colorectal cancer cells." (PMID 35727208, 2022). "In addition, CDK1, HMGB2, SSRP1, and H2AFV may serve as key nodes for HMGB1 in colorectal cancer." (PMID 36230798, 2022). "Recent studies have revealed that HMGB1-RAGE signaling triggers ERK-mediated mitochondrial Drp1 phosphorylation leading to autophagy for chemoresistance and regrowth in colorectal cancer." (PMID 34199060, 2021). "In patients with colorectal cancer (CRC), high serum HMGB1 was positively correlated with lymph node metastasis." (PMID 34867338, 2021). "NETs trigger high mobility group box 1 (HMGB1) release and activate the TLR9 pathway to facilitate tumor cell adhesion, proliferation, migration and invasion in colorectal cancer." (PMID 34116679, 2021). "When colorectal cancer cells were subjected to ICD inducers (mitoxantrone and oxaliplatin), miR-27a-3p blocked CRT exposure, as well as ATP and HMGB1 secretion." (PMID 34073766, 2021). "HMGB1 was shown to promote ERK-mediated mitochondrial DRP1 phosphorylation, thus enhancing chemoresistance through RAGE in colorectal cancer (CRC)." (PMID 33807275, 2021). "Soluble thrombomodulin (TMα), known to degrade HMGB1 in a thrombin-dependent manner, prevents CIPN in rodents treated with paclitaxel, oxaliplatin, or vincristine and in patients with colorectal cancer undergoing oxaliplatin-based chemotherapy." (PMID 33396481, 2020). "In colorectal cancer cells, oxaliplatin combined with MTF resulted in synergistic cytotoxicity, and limited expression of high mobility group box 1 (HMGB1), which is a regulator of cell death and survival." (PMID 30241339, 2018). "Both NK cell-derived HMGB1 and, as a comparison, recombinant human HMGB1 efficiently killed SW480 and HCT116 colorectal cancer (CRC) cells, respectively." (PMID 26948869, 2016). "However, the diagnostic significance of HMGB1 has not been evaluated in colorectal carcinomas." (PMID 22496788, 2012). "Furthermore, in colorectal cancer cells, NET-derived HMGB1 was shown to interact with TLR9 with the subsequent activation of MAP kinase pathway." (PMID 41142788, 2025). "Furthermore, HMGB1 has been shown to promote EMT in various human cancers, such as osteosarcoma and colorectal cancer." (PMID 41194272, 2025). "Therefore, the HMGB1/BECN1 axis, which is critical for colorectal cancer progression, can represent a therapeutic marker for patients with CRC, particularly those with radioresistance." (PMID 41164196, 2025). "Thus, we propose that NE expressed by ADVNE and PPE expressed by ADVPPE activate Caspase-3 in colorectal cancer cells, which in turn cleaves GSDME to release N-GSDME, thereby inducing pyroptosis and increasing HMGB1 release." (PMID 40082916, 2025). "In addition to pancreatic cancer, increased autophagy mediated by the HMGB1/RAGE axis has been observed in renal cell carcinoma, colorectal cancer, and clear cell renal cell carcinoma." (PMID 38529373, 2024). "The HMGB1-RAGE axis activates the phosphorylation of dynamin-related protein 1 (Drp1) leading to mitochondrial fission and cell autophagy, which promotes chemotherapy resistance and tumor growth in colorectal cancer." (PMID 38529373, 2024).
colorectal cancer (continued). "Therefore, we investigated naphplatin modulate HMGB1-meditated CTSL and autophagy-lysosome programs modulated by naphplatin in colorectal cancer." (PMID 37537587, 2023). "However, Gao Tan’s study found that HMGB1, a proinflammatory factor released from GSDME-mediated pyroptotic epithelial cells, induces colorectal cancer proliferation through the ERK1/2 pathway." (PMID 37211606, 2023). "HMGB1/receptor for advanced glycation end product (RAGE)/Erks signal triggers the activation of Drp1, inducing LC3 and p62-dependent mitophagy for chemoresistance in colorectal cancer cells." (PMID 34868997, 2021). "Results of a meta-analysis revealed that overexpression of tissue HMGB1 correlated with clinical stage, depth of invasion, lymph node involvement and distant metastasis in Asian patients with colorectal cancer." (PMID 32664328, 2020). "It has been reported that L-OHP also can upregulate the expression of HMGB1 in colorectal cancer cells, but our results show that L-OHP neither upregulated the expression of CXCL11 nor stimulated the release of HMGB1 in A549 and H460 cells." (PMID 30744691, 2019). "This panel of TKIs indeed induced signs of ICD such as immunofluorescence-detectable CALR exposure and the release of ATP and HMGB1 into the culture supernatant in several human cancer cell lines (U2OS, cervical carcinoma HeLa, colorectal cancer HCT-116) and in murine fibrosarcoma MCA205 cells." (PMID 30940805, 2019). "In this study, the role of HMGB1 in CRC tumor cell proliferation induced by irradiated dying cells was investigated in vitro, and the clinical significance of HMGB1 expression in colorectal cancer patients was analyzed by comparing its expression with the expression of CC3, RAGE, and Ki67." (PMID 25986235, 2015). "High mobility group box 1 (HMGB1), released from GSDMC‐mediated pyroptotic tumor cells, upregulates CXCL2 expression in adjacent tumor cells, thereby recruiting myeloid‐derived suppressor cells (MDSCs) into the tumor microenvironment (TME) to promote colorectal cancer progression." (PMID 40213993, 2025). "We found that by promoting HMGB1 cytosolic translocation and inhibition of Beclin-1-PI3K-III core complex formation through the MEK/ERK1/2 pathway, naphplatin modulates CTSL and autophagy-lysosome function and enhances its sensitivity towards colorectal cancer." (PMID 37537587, 2023). "All these results suggest that naphplatin can promote HMGB1 cytosolic translocation and inhibits Beclin-1-PI3K-III core complex formation through the MEK/ERK1/2 pathway to modulate CTSL and autophagy-lysosome function, which therefore enhances the sensitivity of colorectal cancer to naphplatin." (PMID 37537587, 2023). "The release of HMGB1 from dying cancer cells enhances regrowth and chemoresistance via RAGE-ERK signaling, and the RAGE-ERK pathway activates the phosphorylation of Drp1 at residue S616, thus triggering autophagy for chemoresistance and regrowth in surviving colorectal cancer cells." (PMID 34199060, 2021). "Altogether, our findings showed that the HMGB1-induced Drp1-dependent mitochondrial dynamics via RAGE-ERK signaling pathway for autophagy and chemoresistance could be candidate therapeutic targets for new treatment strategies in colorectal cancer." (PMID 30258050, 2018). "Unlike CEA, elevated serum HMGB1 was also frequently observed in early-stage colorectal cancer." (PMID 22496788, 2012). "Although HMGB1 was reported to be related with poor prognosis in colorectal carcinoma tissues in an earlier report, we could not compare HMGB1 levels in cancer tissue by immunohistochemistry because most of the tumor cells exhibited HMGB1 overexpression." (PMID 22496788, 2012). "This may justify some data from Cis-treated colorectal cancer cells, which showed an increase in HMGB1 but no alteration in CRT exposure, probably because ICD-associated DAMPs were assessed in the context of late apoptosis so that the peak of CRT exposure was lost." (PMID 32456685, 2020).